SLC38A8 (solute carrier family 38 member 8)
Description:
Electrogenic sodium-dependent amino acid transporter with a preference for L-glutamine, L-alanine, L-histidine, L-aspartate and L-arginine. May facilitate glutamine uptake in both excitatory and inhibitory neurons. The transport mechanism and stoichiometry remain to be elucidated.
Synonyms: SNAT8; FHASD; FVH2
Tractability: Antibody: UniProt predicts a signal peptide or a membrane-spanning region.
Gene: Protein-coding gene on chromosome 16 (84,009,667 to 84,043,143, reverse strand). Ensembl gene ENSG00000166558.
Subcellular location: Membrane; Cytoplasm, cell cortex; Cell projection, axon
Gene Ontology:
Molecular function: L-amino acid transmembrane transporter activity
Biological process: amino acid transmembrane transport; L-alpha-amino acid transmembrane transport
Cellular component: membrane; axon; cell cortex
Genetic constraint (gnomAD): Loss-of-function variants: 67 observed, 48.97 expected, observed/expected ratio (o/e) 1.37, 90% interval 1.12 to 1.68. The synonymous counts are far from expectation, so gnomAD's model fits this gene poorly and the ratio says little. Missense variants: 998 observed, 594.14 expected, observed/expected ratio (o/e) 1.68, 90% interval 1.59 to 1.77. Synonymous variants: 447 observed, 254.12 expected, observed/expected ratio (o/e) 1.76, 90% interval 1.63 to 1.9.
Gene-disease validity (ClinGen):
ClinGen rates the evidence that SLC38A8 causes each of these diseases.
foveal hypoplasia - optic nerve decussation defect - anterior segment dysgenesis syndrome (autosomal recessive): Definitive.
Homologues: Orthologues: chimpanzee SLC38A8 (96% identical), macaque SLC38A8 (96% identical), dog SLC38A8 (84% identical), pig SLC38A8 (83% identical), rabbit SLC38A8 (82% identical), mouse Slc38a8 (82% identical), guinea pig SLC38A8 (79% identical), rat Slc38a8 (77% identical), zebrafish slc38a8b (56% identical), zebrafish slc38a8a (54% identical), Drosophila melanogaster CG32079 (17% identical), Drosophila melanogaster mah (15% identical), and 15 more. Paralogues in human: SLC38A7 (40% identical), SLC38A3 (23% identical), SLC38A5 (22% identical), SLC38A2 (22% identical), SLC38A1 (20% identical), SLC38A4 (20% identical), SLC38A6 (20% identical), SLC38A11 (19% identical), SLC38A10 (18% identical), SLC38A9 (17% identical), SLC36A1 (17% identical), SLC36A4 (17% identical), and 3 more.
Diseases named in the same sentence as SLC38A8 in open-access papers:
SLC38A8 is named in the same sentence as 25 diseases in open-access papers, as found by Europe PMC text mining. Sharing a sentence is not in itself a finding about the gene and the disease. The quoted sentences say what the papers report.
albinism (9 papers, 2014 to 2025). A congenital disorder characterized by partial or complete absence of melanin pigment in the eyes, hair, or skin. "The identification of only 3e patients with mutations in SLC38A8 in a series of 990 presumed patients with albinism, and only 61 patients with FHONDA reported to date confirm that this is a rare entity." (PMID 35029636, 2022). "Differential diagnoses must include SLC38A8-associated foveal hypoplasia and syndromic forms of albinism." (PMID 33808351, 2021). "In a large French cohort of suspected cases of albinism, SLC38A8 mutations were identified in 0.4% (4/990) cases." (PMID 32744312, 2020). "However, once chiasmal misrouting is established on VEP testing, only albinism and SLC38A8 mutations are considered as differentials." (PMID 32744312, 2020). "In addition to FH, PAX6 mutations can be associated with keratopathy, cataracts, glaucoma and optic nerve hypoplasia thus resulting in much more reduced vision compared with SLC38A8 mutations and albinism." (PMID 32744312, 2020). "A multicentre study of 907 patients with FH found that 67% of individuals had albinism caused by variants in GPR143, OCA2, TYR and HPS1 genes, followed by 21.8% with PAX6, 6.8% with SLC38A8 and 3.5% with FRMD7 variants." (PMID 37762234, 2023). "Mutations in SLC38A8 cause ocular characteristics of albinism without affecting pigmentation and lead to altered glutamate and glutamine metabolism." (PMID 40585125, 2025). "SLC38A8-oculopathy may well be under diagnosed because of its subtle presentation, easily confused with albinism." (PMID 33498813, 2021). "Four unrelated families (56, 26350, 58, and 26364) were identified with biallelic SLC38A8 (OMIM #615585) variants through WGS (as this gene is not present on targeted gene panels for nystagmus or albinism)." (PMID 32830442, 2020). "A notable finding for patients with query albinism and infantile nystagmus, was that a number of genes were found in both subgroups, including OCA2 and SLC38A8." (PMID 32830442, 2020). "The genes identified for MAC were KMT2D, MAB2IL2, ALDH1A3; ASDA were KERA, PAX6, MYOC, TGFBI, and SLC4A11; congenital cataract were CRYBB2, EPHA2, HSF4 and BCOR; infantile nystagmus were CACNA1A and FRMD7; and albinism were OCA2, GPR143, HPS6 and SLC38A8." (PMID 32830442, 2020). "Unlike other disorders (such as albinism or PAX6 mutations) which exhibit a spectrum of foveal hypoplasia, SLC38A8 mutations have arrest of retinal development at an earlier stage resulting in a more under-developed retina and severe phenotype." (PMID 32744312, 2020). "Until recently, SLC38A8 was not included in the albinism and nystagmus targeted gene panels." (PMID 33498813, 2021).
Nystagmus (7 papers, 2019 to 2024). Rhythmic, involuntary oscillations of one or both eyes related to abnormality in fixation, conjugate gaze, or vestibular mechanisms. "All probands with SLC38A8-associated foveal hypoplasia had evidence of nystagmus, foveal hypoplasia, and intracranial misrouting." (PMID 33808351, 2021). "In this multi-centre study, a custom-targeted next generation sequencing (NGS) gene panel was used to identify SLC38A8 mutations from a cohort of 511 nystagmus patients." (PMID 32744312, 2020). "SLC38A8 mutations share similar nystagmus characteristics to other forms of IN suggesting a common pathophysiological mechanism." (PMID 32744312, 2020). "The ‘TruSight One Expanded v3.0’ has also expanded on the original TruSight One capture to cover other known nystagmus-causing genes such as SLC38A8." (PMID 31519934, 2019). "In most patients with SLC38A8 mutations, we observe a jerk nystagmus." (PMID 32744312, 2020). "Equally, loci associated with foveal hypoplasia, nystagmus and hypopigmentation (AHR, FRMD7, GPR143, and SLC38A8) were assessed for SNV or SV segregating with disease." (PMID 38383453, 2024). "Biallelic pathogenic variants in solute carrier family 38 member 8, SLC38A8, cause a pan-ocular autosomal recessive condition known as foveal hypoplasia 2, FVH2, characterised by foveal hypoplasia, nystagmus and optic nerve chiasmal misrouting." (PMID 33498813, 2021). "The detailed phenotypical characteristics including nystagmus features and degree of arrested retinal development in SLC38A8 mutations have not been systematically analyzed in relation to genotypes." (PMID 32744312, 2020).
foveal hypoplasia (4 papers, 2017 to 2022). Underdevelopment of the fovea centralis. "Molecular analysis showed point mutations in TYR in all patients analyzed, and none of them presented sequence alterations or copy number variants (CNVs) in PAX6, SLC38A8 or in other genes associated with foveal hypoplasia." (PMID 35887175, 2022).
congenital nystagmus (2 papers, 2020 to 2021). Nystagmus present at birth or caused by lesions sustained in utero or at the time of birth. "Additionally, SLC38A8 contributes to congenital nystagmus, and RIMS1 and CABP4 are associated with dystrophy and synaptic disorder of cone-rod, respectively." (PMID 33330132, 2020).
Obesity (2 papers, 2023). Accumulation of substantial excess body fat. "SLC38A8 has a high GWAS Catalog score (14.1) with adiponectin measurement, which directly affects insulin sensitivity and obesity, and a strong association with eye diseases, e.g. foveal hypoplasia 2 and anterior segment dysgenesis." (PMID 37205363, 2023). "The link from gene SLC38A8 to both obesity and facial features may imply a novel relationship between obesity and facial morphology." (PMID 37205363, 2023).
oculocutaneous albinism (2 papers, 2020 to 2021). Oculocutaneous albinism (OCA) describes a group of inherited disorders of melanin biosynthesis characterized by a generalized reduction in pigmentation of hair, skin and eyes and variable ocular findings including nystagmus, reduced visual acuity and photophobia. "Recessive mutations in the SLC38A8 (solute carrier family 38 member 8) gene on chromosome 16q23.3 have been shown, however, to cause FVH and optic nerve misrouting independent of the pigmentation defects associated with oculocutaneous albinism or ocular albinism." (PMID 33498813, 2021).
X-linked ocular albinism (2 papers, 2019 to 2020). "One participant had GPR143-associated X-linked ocular albinism and another proband had biallelic variants in SLC38A8, a glutamine transporter gene associated with foveal hypoplasia and optic nerve misrouting without pigmentation defects." (PMID 31719542, 2019).
Astigmatism (1 paper, 2020). A type of refraction error associated with abnormal curvatures on the anterior and/or posterior surface of the cornea. "Taken together, this suggests that patients with SLC38A8 mutations almost always have significant WTR astigmatism." (PMID 32744312, 2020).
developmental delay (1 paper, 2014). "SLC38A8 mutations are also associated with developmental delay and pervasive developmental disorder-like features." (PMID 24688117, 2014).
Horizontal nystagmus (1 paper, 2021). Nystagmus consisting of horizontal to-and-fro eye movements. "A three-year-old girl in Family 39 with congenital horizontal nystagmus had compound heterozygous variation of SLC38A8, and her parents were heterozygous carriers of the variant." (PMID 33781268, 2021).
partial albinism (1 paper, 2019). "Notably, one patient in in the present study had SLC38A8-associated disease, an important differential diagnosis of partial albinism." (PMID 31719542, 2019).
retinopathy of prematurity (1 paper, 2023). A bilateral retinopathy characterized by neovascularization, scarring, retinal detachment, and eventually blindness. "This particular appearance of the fovea can be associated with conditions such as albinism, PAX6 mutation, aniridia, retinopathy of prematurity (ROP), SLC38A8 mutations, optic nerve hypoplasia, achromatopsia, and cone-rod dystrophy, but can also be found in normal children." (PMID 36836571, 2023).
viral infection (1 paper, 2023). "Viral infection is a complicated process, which may affect cellular microenvironment or activate a series of signaling pathways to alter the affinity of SLC38A8 for amino acids, resulting in high levels of aspartate uptake by SLC38A8 during FMDV infection." (PMID 36735752, 2023).
infection (1 paper, 2023). The state of being infected such as from the introduction of a foreign agent such as serum, vaccine, antigenic substance or organism. "Meanwhile, EV71 and SVV enhanced the protein expression of SLC38A8 as the infection progressed." (PMID 36735752, 2023).
tumor (1 paper, 2023). "By analyzing TCGA data in the GEPIA database, we found that the expression levels of multiple SLC38A family members (including SLC38A2, SLC38A4, SLC38A5, SLC38A6, SLC38A7, SLC38A8, SLC38A9, and SLC38A10) were significantly upregulated in GC tumor tissues." (PMID 36918802, 2023).
SLC38A8 also shares sentences with these, for which no sentence is quoted: cataract (2 papers); FHONDA) syndrome (2); cancer (1); congenital cataract (1); glaucoma (1); macular degeneration (1); ocular albinism (1); optic nerve hypoplasia (1); pervasive developmental disorder (1); retinitis pigmentosa (1).